OIP5 (Opa interacting protein 5)
Diseases named in the same sentence as OIP5 in open-access papers (continued):
Sharing a sentence is not in itself a finding about the gene and the disease.
tumor (continued). "Collectively, OIP5 expression enhanced cell migration and invasiveness, whereas OIP5 suppression appeared to inhibit the migration and invasiveness of tumor cells in vitro." (PMID 28184024, 2017). "In contrast to neoantigen-based vaccines, which focus on targeting mutation-specific antigens unique to individual tumors, our multi-epitope vaccine targets conserved tumor-associated antigens (DKKL1, FBXO39, and OIP5) that are widely expressed across CRC patients." (PMID 40599850, 2025). "Similarly to OIP5, PBK expression correlates with features of genomic instability such as high tumor mutational burden and microsatellite instability." (PMID 38596293, 2024). "Moreover, OIP5 likely regulates cell cycle progression in a tumor-type specific manner, affecting either G0/G1, G2/M or G1/S transition, leading to apoptosis and senescence." (PMID 38596293, 2024). "Furthermore, OIP5 is also involved in regulating the proliferation, migration, invasion, apoptosis and other biological behaviors of tumor cells, thus promoting the occurrence and development of tumors." (PMID 37660035, 2023). "Furthermore, the expression pattern of OIP5 was found to gradually increase when the tumor pathological grade increased and then decreased (Stages II and III began to decline)." (PMID 36661650, 2022). "In conclusion, it is speculated that OIP5 inhibitors may also enhance tumor immunity from a biological perspective, thus contributing to the anti-tumor efficacy of immune checkpoint blockers." (PMID 35242130, 2022). "Our results provided insights into the role of OIP5 in tumor immunity and revealed that OIP5 may be a potential immunotherapeutic target for ccRCC." (PMID 35242130, 2022). "Our results showed that OIP5 was highly expressed in ccRCC and high expression of OIP5 gene was correlated significantly with the patient’s age, the tumor histological grade, T classification, N classification, M classification and clinical stage, which was consistent with our previous findings." (PMID 35242130, 2022). "OIP5 promotes pRCC cell proliferation and tumor formation through complex processes." (PMID 34503297, 2021). "Inhibition of PLK1 significantly increases the survival of mice bearing ACHN OIP5 tumor." (PMID 34503297, 2021). "Furthermore, PLK1 is a component gene of Overlap66; PLK1 inhibitor significantly reduced OIP5-promoted pRCC cell proliferation in vitro and tumor growth in vivo." (PMID 34503297, 2021). "In comparison to AJK tissues, pRCC tumor tissues expressed a significant OIP5 upregulation." (PMID 34503297, 2021). "Immunohistochemical (IHC) staining for OIP5 in various HCC tissues revealed that OIP5 was moderately expressed in tumors compared to the much lower expression levels observed in surrounding non-tumor and normal liver tissues." (PMID 28184024, 2017). "CDM only partially inhibited OIP5-dependent tumor cell growth." (PMID 28184024, 2017). "Mass-forming tumors with intrahepatic tumor nodules were easily detected in the livers of mice injected with parent or non-target control cells, whereas only a few intrahepatic tumor nodules were found in mice injected with OIP5-knockdown cells." (PMID 28184024, 2017). "Our finding of PLK1 inhibitor being effective in inhibition of ACHN OIP5 tumor growth may have significant clinical applications in treating metastatic pRCC with OIP5 upregulation; this will offer a venue for potential utilization of personalized therapy in pRCC." (PMID 34503297, 2021). "Linc-OIP5 may have a certain relationship with tumor resistance and metastasis." (PMID 32046779, 2020). "We assessed the expression of PINK1.AS, OIP5.AS1, HID.AS1, and MAPT.AS1 in tumor pairs using qRT-PCR, which revealed a marked increase in the expression of these chrlncRNAs in tumor tissues compared to adjacent tissues." (PMID 38326441, 2024). "OIP5 regulated the proangiogenic effect of HUVECs cells through the Notch signaling pathway in the microenvironment of TNBC tissue and thus promoted tumor cell metastasis." (PMID 33443534, 2021).
tumor (continued). "To investigate this possibility, we examined OIP5 expression in pRCC using a tissue microarray (TMA) containing 40 pairs of pRCC and 74 pairs of ccRCC tumors with the adjacent non-tumor kidney (AJK) tissues from 20 and 37 patients, respectively." (PMID 34503297, 2021). "When the Wilcoxon signed-rank test was used, we noted that 6 of 18 (33%) CTAs tested, MAGEA3, OIP5, TTK, PLU1, DKKL1, and FBXO39, were significantly (p < 0.05) overexpressed in the tumor compared with normal tissue located ~5 cm away from the primary lesion." (PMID 27635108, 2016). "Moreover, IHC staining was performed on the subcutaneous tumor tissues of mice in which YTHDC1 was downregulated, and it was found that OIP5 expression was lower in the kd-YTHDC1 group, while GPD1L expression was increased." (PMID 38573528, 2024). "OIP5 was highly expressed in HCC (75%) compared with non-tumor tissue, in 12 HCC/non-tumor tissue pairs." (PMID 28184024, 2017). "Microarray data derived from the Gene Expression Omnibus (GEO) database (GSE36411), containing 42 HCCs and corresponding non-tumor tissues, revealed that OIP5 expression in HCC tissue was significantly higher than expression in matched non-tumor tissues surrounding the liver." (PMID 28184024, 2017).
infection (2 papers, 2014 to 2017). The state of being infected such as from the introduction of a foreign agent such as serum, vaccine, antigenic substance or organism. "Transient expression of OIP5 by infection with Ad-OIP5 also increased the phosphorylation of AKT1 and AKT2 in HLK3 and SH-J1 cells." (PMID 28184024, 2017). "Oip5 mRNA level was hardly influenced by the infection of Ad-βgal compared to the non-infected cells (data not shown)." (PMID 24516558, 2014).
OIP5 also shares sentences with these, for which no sentence is quoted: clear cell renal cell carcinoma (4 papers); renal cell carcinoma (2); acute myeloid leukemia (1); autoimmune thyroid disease (1); Cirrhosis (1); connective tissue disease (1); Digestive system disease (1); estrogen-receptor negative breast cancer (1); head and neck squamous cell carcinoma (1); liver cirrhosis (1); malignant glioma (1); melanoma (1); multiple myeloma (1); oral cancer (1); prostate carcinoma (1); triple-negative breast carcinoma (1); type 2 diabetes (1); urogenital cancers (1); uterine cancer (1).